BUB1 (BUB1 mitotic checkpoint serine/threonine kinase)
Diseases named in the same sentence as BUB1 in open-access papers (continued):
Sharing a sentence is not in itself a finding about the gene and the disease.
osteosarcoma (9 papers, 2013 to 2025). A usually aggressive malignant bone-forming mesenchymal neoplasm, predominantly affecting adolescents and young adults. "Later, BUB1 was determined as the kinase consistently overexpressed across the osteosarcoma, liposarcoma, leiomyosarcoma, and synovial sarcoma." (PMID 40723917, 2025). "Inhibition of BUB1 suppresses cell proliferation, and tumor growth, cell migration, and invasion and induces apoptosis of osteosarcoma cells by blocking the PI3K/AKT and ERK signalling pathways." (PMID 36787437, 2023). "In osteosarcoma, inhibition of BUB1 markedly suppressed cell proliferation, cell migration, and invasion through blocking of the PI3K/Akt and ERK signaling pathways." (PMID 35859724, 2022). "The overexpressed kinases in osteosarcoma, liposarcoma, and leiomyosarcoma are mainly serine/threonine kinases (BUB1, CKD4, HUNK, LKKK1, NEK2, PBK, PLK1, and PLK4), whereas TTK has a dual role (Tyrosine and serine/threonine kinase) and only MELK presents tyrosine phosphorylation activity." (PMID 40723917, 2025). "Recently, BUB1 overexpression in osteosarcoma was demonstrated using cell lines and tissue samples." (PMID 40723917, 2025). "In a study on osteosarcoma, it was pointed out that RFC3, CDK1, MAD2L1, NDC80, BUB1, etc. jointly participated in the related links of the disease prognosis of osteosarcoma." (PMID 35483337, 2022). "In the PPI network, we selected six genes (CDK1, CCNB2, CDC20, CCNA2, BUB1, and AURKB) as the core STIL differentially co-expressed genes in osteosarcoma." (PMID 33858425, 2021). "Using the 13 gene chips, we found that six hub differentially co-expressed genes (CDK1, CCNB2, CDC20, CCNA2, BUB1, and AURKB) were highly expressed in osteosarcoma." (PMID 33858425, 2021). "STIL is associated with osteosarcoma proliferation and invasion, and may be promote the progression of osteosarcoma by regulating the expression of CDK1, CCNB2, CDC20, CCNA2, BUB1 and AURKB." (PMID 33858425, 2021). "Moreover, the bioinformatics analysis showed that STIL may participate in the biological function of osteosarcoma by regulating CDK1, CCNB2, CDC20, CCNA2, BUB1, and AURKB." (PMID 33858425, 2021). "Using osteosarcoma cells (U2OS) and normal human dermal fibroblast (HDF), two well-established models for the study of chromosome congression, we demonstrate that miR-155 targets the spindle checkpoint proteins BUB1, CENP-F, and ZW10, thus compromising chromosome alignment at the metaphase plate." (PMID 29560129, 2018).
colon carcinoma (8 papers, 2006 to 2023). "BUB1 variants have in addition to colon cancer been associated with mosaic variegated aneuploidy syndrome (MVAS), due to BUB1’s role as a component of the spindle assembly checkpoint, and dysmorphic features." (PMID 33193653, 2020). "miR-4727-3p has been shown to bind with the BUB1 gene, lower expression levels of which have previously been shown to be associated with shorter relapse-free survival after surgery for colon carcinoma." (PMID 29084506, 2017). "In colon carcinomas reduced BUB1 mRNA levels were associated with shorter relapse-free survival after surgery." (PMID 29100315, 2017). "We decided to further evaluate the consequences of Bub1 inhibition on mitosis using the DLD-1 colon cancer cell line, which maintains a ‘flatter’ morphology during mitosis allowing easy visualization of chromosomes." (PMID 34925867, 2021). "Here we found, following time-lapse imaging of DLD-1 colon cancer cells, that Bub1 inhibition with 10 μM BAY-320 resulted in an albeit minor but significantly increased time to complete mitosis compared with untreated cells." (PMID 34925867, 2021). "If the APC gene is mutated, truncated proteins may lose their ability to bind to Bub1 and fail to properly maintain microtubule attachment to the kinetochore, leading to defects in chromosome segregation, which then leads to poor prognosis in Colon cancer patients." (PMID 37916187, 2023). "Conversely, we found that 6 genes involved in the mitotic spindle checkpoint (TTK, BUB1, BUB3, CDC20, MAD2L1, and BUB1B) are overexpressed in colon cancer specimens." (PMID 16919171, 2006).
glioma (8 papers, 2011 to 2025). A benign or malignant brain and spinal cord tumor that arises from glial cells (astrocytes, oligodendrocytes, ependymal cells). "For example, BUB1 is a mitotic checkpoint that can promote the proliferation of glioma cells and radioactive resistance and is directly associated with poor prognosis of glioma patients." (PMID 34631884, 2021). "Overexpression of BUB1 contributes to the morphological progression of clear cell renal carcinoma Shen YL’s research showed that GINS2 can accelerate the growth of glioma cells." (PMID 37745716, 2023). "BUB1, as a novel therapeutic target for glioma can promote the proliferation and radio-resistance ability of glioma." (PMID 34556022, 2021). "BUB1 is a gene signature that have a key effect on glioma stem cells after evaluating mRNA expression in glioma patient samples using The Cancer Genome Atlas and constructing DEGs co-expression networks of glioma samples by weighted gene co-expression network analysis." (PMID 38167011, 2024). "In glioma, KIF4A enhances the expression of BUB1, activating the TGF-β/SMAD pathway, which promotes EMT and malignant progression." (PMID 41361459, 2025). "Through gene correlation analysis, we identified genes positively correlated with CKAP2L, including BUB1, TTK, and ASPM, which can promote the development of glioma and treatment resistance." (PMID 34631884, 2021). "Expression of six SAC genes, BUB1, BUB1B, CDC20, CENPE, MAD1L1 and TTK were found to be significantly positively correlated with WHO grades of glioma patients (p<0.01)." (PMID 22022424, 2011). "RNA levels of eight major mitotic spindle assembly checkpoint (SAC) genes (BUB1, BUB1B, BUB3, CENPE, MAD1L1, MAD2L1, CDC20, TTK) significantly correlated with glioma grade and six also significantly correlated with survival time." (PMID 22022424, 2011). "In conclusion, two SAC genes, BUB1 and TTK, showed increased RNA expression compared to normal brain even in the lowest grades of glioma, perhaps indicating their future utility for differentiating among low grade gliomas." (PMID 22022424, 2011). "BUB1 and TTK were significantly differentially expressed between low grade gliomas and normal brain tissues (p<0.01)." (PMID 22022424, 2011). "Interestingly, Ki-67 RNA level was outperformed by BUB1B and CDC20, overall, and by BUB1 and TTK when applied to grade II gliomas." (PMID 22022424, 2011).
Lipedema (5 papers, 2022 to 2025). Disorder of adipose tissue characterized by symmetric and bilateral enlargement of the lower extremities due to abnormal deposition of subcutaneous fat often in obese women. "One upregulated gene in lipedema ADSCs, Bub1, encodes a cell-cycle regulator, central to the kinetochore complex, which regulates several histone proteins involved in cell proliferation." (PMID 34764426, 2022). "Disruptions within key signaling networks, particularly the Bub1 signaling pathway, have been implicated in the hyperproliferation of adipose-derived stem cells, suggesting a molecular mechanism underlying increased adipogenesis in lipedema." (PMID 40419722, 2025). "Downstream signaling analysis of lipedema ADSCs showed enhanced activation of histone H2A, a critical driver of cell proliferation and a target of Bub1." (PMID 40425048, 2025). "This aligns with previous studies and recent findings linking Bub1 gene dysregulation to increased proliferation and angiogenesis in the adipose tissue of patients with lipedema." (PMID 40077894, 2025). "Dysregulated signaling networks, such as those involving the cell cycle regulator Bub1, drive the increased proliferation of adipose-derived stem cells in lipedema." (PMID 40419722, 2025). "Validation of the eight most promising genes involved in mitotic spindle checkpoint regulation by qRT-PCR identified Bub1 as a potential key mediator of mitotic spindle checkpoint pathways in lipedema tissue and ADSCs." (PMID 34764426, 2022). "Downstream signaling analysis of lipedema ADSCs demonstrated enhanced activation of histone H2A, a key cell proliferation driver and Bub1 target." (PMID 34764426, 2022). "Critically, hyperproliferation exhibited by lipedema ADSCs was inhibited by the small molecule Bub1 inhibitor 2OH-BNPP1 and by CRISPR/Cas9-mediated Bub1 gene depletion." (PMID 34764426, 2022). "Among the genes related to cell mitotic pathways regulating the spindle-assembly checkpoint, whose expressions were altered in lipedema ADSCs, BUB1 was found to be of particular interest." (PMID 36551837, 2022). "As transcriptional profiling has found BUB1 to be an essential target regulating cellular proliferation in lipedema ADSCs, researchers have used a CRISPR/Cas-9 lentiviral system to knock down BUB1, which decreases the proliferation of lipedema ADSCs." (PMID 36551837, 2022). "Excitingly, either 2OH-BNPP1 treatment or CRISPR/Cas9-mediated Bub1 gene depletion can dramatically reduced lipedema ADSC proliferation." (PMID 34764426, 2022). "Functional assays demonstrated that dysregulated Bub1 signaling drives increased proliferation of lipedema ADSCs, suggesting a potential mechanism for enhanced adipogenesis in lipedema." (PMID 34764426, 2022). "Using gene expression analysis and cell-based bioassays, we identified Bub1 as a novel therapeutic target in lipedema for which a small molecule inhibitor has been successfully tested in pre-clinical cancer models." (PMID 34764426, 2022). "Of note, Bub1, also known as Benzimidazole 1, was found to be upregulated in lipedema ADSCs." (PMID 40425048, 2025). "Our finding that Bub1 mRNA is overexpressed in lipedema ADSCs suggested to us that Bub1 may play a similar role in lipedema as it does in cancer (i.e., driving excessive cell proliferation), and could therefore be a potential therapeutic target." (PMID 34764426, 2022). "Consequently, we sought to analyze Bub1 transcript levels in ADSCs from lipedema and non-lipedema patients by qRT-PCR, which demonstrated that Bub1 mRNA was significantly upregulated in lipedema ADSC populations, compared to controls." (PMID 34764426, 2022). "The higher Bub1 expression in lipedema tissue and ADSCs may act to disrupt G1/S checkpoint inhibition resulting in increased cell proliferation." (PMID 34764426, 2022). "Importantly, our characterization of signaling networks driving lipedema identifies potential molecular targets, including Bub1, for novel lipedema therapeutics." (PMID 34764426, 2022).
Lipedema (continued). "Treatment of both ADSC groups with 2OH-BNPP1 revealed marked reduction of histone H2A phosphorylation at T120, a novel and important finding that suggested that the effect of Bub1 in lipedema is mediated by its capacity to phosphorylate downstream targets such as histone H2A." (PMID 34764426, 2022). "Importantly, the Bub1 downstream target histone H2A, phosphorylation of which is considered important for cell proliferation, was more highly phosphorylated in lipedema ADSCs." (PMID 34764426, 2022). "Mitosis also plays a role in balancing stem cells between the states of self-renewal and differentiation from progenitor to mature cells by regulating symmetric and asymmetric division; hence, Bub1 upregulation in lipedema may contribute to abrogation of stem cell homeostasis." (PMID 34764426, 2022). "Treatment of lipedema ADSCs with 2OH-BNPP1 also profoundly inhibited histone H2A phosphorylation, further supporting a key role for Bub1 in enhanced ADSC proliferation and pathological adipogenesis in lipedema." (PMID 34764426, 2022). "To ascertain the effects of restricting Bub1 in lipedema ADSCs, we employed a CRISPR/Cas9-mediated lentiviral system to knockdown Bub1 and a small molecule Bub1 inhibitor." (PMID 34764426, 2022). "To explore a pharmacological approach for inhibiting Bub1 in lipedema ADSCs, we next employed the small molecule 2OH-BNPP1, which specifically inhibits the Serine/Threonine kinase activity of Bub1." (PMID 34764426, 2022). "Notably, hyperproliferation in lipedema ADSCs was suppressed by the serine/threonine kinase inhibitor 2OH‐BNPP1, which is a Bub1 inhibitor, and following CRISPR/Cas9‐mediated depletion of the Bub1 gene." (PMID 40425048, 2025). "Our data indicate that Bub1 overexpression promotes ADSC hyperproliferation in lipedema and may therefore play a key role in lipedema disease onset and progression." (PMID 34764426, 2022). "As expected, knockdown of Bub1 gene decreased proliferation of both lipedema and non-lipedema ADSCs; however, the reduction in proliferation was significantly more pronounced in lipedema ADSCs." (PMID 34764426, 2022).
multiple myeloma (5 papers, 2020 to 2023). "In this study, we identified aberrant overexpression of BUB1 in myeloma cells, which associates with disease progression and aggressiveness." (PMID 32781708, 2020). "Understanding the functional significance of BUB1 overexpression may lead to new diagnostic and therapeutic approaches to overcome myeloma progression." (PMID 32781708, 2020). "A further study is needed to determine the mechanism linking the clonal evolution of myeloma cells with BUB1 dysregulation, which may lead to new diagnostic and therapeutic approaches to limit myeloma progression." (PMID 32781708, 2020). "Thus, further research is needed to clarify the mechanism underlying BUB1-mediated clonogenicity and tumorigenesis in myeloma cells, and this may also lead to the discovery of a novel therapeutic target, which could be functionally synthetic lethal." (PMID 32781708, 2020). "Overexpression of BUB1 influences the progression of multiple myeloma by promoting mitotic segregation errors and chromosomal instability." (PMID 34298705, 2021). "We also showed that BUB1 overexpression promoted clonogenic potency in myeloma cells, as well as CIN, through an increase of various types of mitotic chromosomal segregation errors." (PMID 32781708, 2020). "BUB1 mRNA tended to be higher in CD138-positive myeloma cells from MGUS and NDMM compared to normal plasma cells, but the difference was not significant." (PMID 32781708, 2020). "Given this scenario, further investigation using a disease model in which the development of de novo myeloma can be observed is needed to examine the function of BUB1." (PMID 32781708, 2020). "In this study, we found that BUB1 was overexpressed in patient-derived myeloma cells, and BUB1 expression was significantly higher in patients in an advanced stage compared to those in an early stage." (PMID 32781708, 2020). "This provoked us to investigate the functional involvement of BUB1 in clonogenic potency in myeloma cells." (PMID 32781708, 2020). "In human myeloma-derived cell lines (HMCLs), BUB1 knockdown reduced the frequency of chromosome segregation errors in mitotic cells." (PMID 32781708, 2020). "BUB1 overexpression promotes the clonogenic potency of human myeloma-derived cell lines." (PMID 36787437, 2023). "Because BUB1 expression was higher in myeloma cells from patients with advanced disease and in HMCLs, BUB1 overexpression might be more associated with disease aggressiveness that is usually accompanied by treatment resistance." (PMID 32781708, 2020). "It would be interesting to investigate if the BUB1 expression level may be a surrogate for the degree of CIN in myeloma cells, and thereby, constitute a new prognostic marker." (PMID 32781708, 2020). "In this study, we identified aberrant overexpression of BUB1 in patient-derived myeloma cells." (PMID 32781708, 2020). "We first examined the BUB1 function in the short-term proliferative activity of myeloma cells." (PMID 32781708, 2020). "Collectively, these results indicated that myeloma cells expressed an aberrantly higher level of BUB1, which increased with disease progression and might be associated with transformation and immortalization." (PMID 32781708, 2020). "However, the BUB1 mRNA levels in myeloma cells from patients in an advanced stage RRMM and HMCLs were significantly higher than that in normal plasma cells and higher than that in myeloma cells from patients with early-stage disease (MGUS and NDMM)." (PMID 32781708, 2020).
triple-negative breast carcinoma (5 papers, 2015 to 2025). An invasive breast carcinoma which is negative for expression of estrogen receptor (ER), progesterone receptor (PR), and human epidermal growth factor receptor 2 (HER2). "Higher BUB1 levels are associated with a poor prognosis, especially in patients with triple-negative breast cancer (TNBC)." (PMID 38927028, 2024). "Additionally, BUB1 expression is significantly associated with basal-like and luminal B tumors and in triple-negative breast cancers." (PMID 38863037, 2024). "Similarly, dual targeting of BUB1 with ATR or PARP inhibitors yields synergistic activity against triple-negative breast cancer cells." (PMID 40180891, 2025).
cervical cancer (4 papers, 2017 to 2026). A primary or metastatic malignant neoplasm involving the cervix. "Then, the top 40 hub genes were conducted to evaluate the expression and prognostic values of cervical cancer and 7 upregulated (BUB1, CCNB1, CDK1, AURKB, KIF11, PBK, NUSAP1) and 1 downregulated (ESR1) hub genes were selected to have significant values as biomarkers." (PMID 33682613, 2021). "BUB1 has not been described to be associated with cervical cancer." (PMID 29312619, 2017). "After combination of the expression pattern and survival analysis, eight upregulated hub gens (CCNB1, BUB1, CDK1, AURKB, KIF11, PBK and NUSAP1) stood out with dramatical upregulation in cervical cancer and were significantly correlated with good prognosis of cervical cancer (P < 0.05)." (PMID 33682613, 2021).
colorectal tumors (4 papers, 2013 to 2025). "Specifically, miR‐495‐3p acts as a tumor suppressor in colorectal tumors by negatively regulating key genes involved in cell cycle progression, including TGFβR1, TGFβR2, SMAD4, and BUB1." (PMID 40620190, 2025).
gastric adenocarcinoma (4 papers, 2017 to 2021). "We examined the expression of the mitotic spindle checkpoint protein BUB1 (budding uninhibited by benzimidazoles 1) and Ki-67 protein expression by immunohistochemistry in 218 patients with primary gastric adenocarcinomas." (PMID 29100315, 2017).
lymph node metastasis (4 papers, 2011 to 2023). "Mutations in BUB1, some of which are functional, occur in some cancers, including those that originate in the lung, colon, and are reported to be associated with chromosomal instability and lymph node metastasis, suggesting that silencing of this kinase may mediate aggressive clinical behavior." (PMID 30822312, 2019).
clear cell kidney carcinomas (3 papers, 2014 to 2023). "Overexpression of BUB1 contributes tothe cytogenetic and morphologic progression of clear cell kidney carcinomas." (PMID 25955318, 2015).
esophageal cancer (3 papers, 2019 to 2026). A primary or metastatic malignant neoplasm involving the esophagus. "Previous studies have reported miR-495-3p could target CDK1, cadherin 2, and HMGB1 to display its functional role in various cancers, and BUB1 was demonstrated as the direct target of miR-495-3p in esophageal carcinoma." (PMID 40420658, 2025).
malaria (3 papers, 2020 to 2025). Malaria is a serious and sometimes fatal disease caused by a parasite that commonly infects a certain type of mosquito which feeds on humans. "Mitosis in Plasmodium spp., the causative agent of malaria, is fundamentally different from model eukaryotes, proceeding via a bipartite microtubule organising centre (MTOC) and lacking canonical regulators such as Polo and Bub1 kinases." (PMID 41041543, 2025).